FBXW7 (F-box and WD repeat domain containing 7)
Diseases named in the same sentence as FBXW7 in open-access papers (continued):
Sharing a sentence is not in itself a finding about the gene and the disease.
skin cancer (5 papers, 2012 to 2023). "In skin cancer, studies found that allele-specific deletion of FBXW7 is observed in 7,12-dimethylbenz[a]anthracene (DMBA)/12-O-tetradecanoylphorbol-13-acetate (TPA) induced skin tumor in mice." (PMID 30791487, 2019). "Our results on the skin tumor model lend strong support to the conclusion that Fbxw7 variants contribute to cancer risk." (PMID 22348067, 2012). "We next investigated the possibility that allele-specific deletions in Fbxw7 locus may occur in skin tumors." (PMID 22348067, 2012). "We investigated the possibility that allele-specific losses of Fbxw7 in the NIHBX population may also predict linkage to a skin tumor susceptibility locus in the region containing the Fbxw7 gene on chromosome 3." (PMID 22348067, 2012). "To clarify the role of Fbxw7 in epithelial cancer development, we investigated the consequences of Fbxw7 deficiency in the DMBA/TPA mouse model of skin cancer development." (PMID 22348067, 2012). "This denotes that deregulation of FBXW7 is involved in the development of skin cancer." (PMID 30791487, 2019). "Gene copy number changes at the Fbxw7 locus were examined by quantitative PCR (TaqMan) analysis of skin tumors from interspecific backcross mice derived by crossing male Spretus/Gla with female mice of the NIH/O strain that carry the G and A alleles respectively." (PMID 22348067, 2012).
adult T-cell leukemia (4 papers, 2020 to 2023). "However, recent studies have identified novel oncogenic FBXW7 mutations in human T-cell leukemia virus (HTLV-I) transformed adult T-cell leukemia (ATL) cells, suggesting a possible carcinogenic role for FBXW7." (PMID 37408248, 2023). "In adult T-cell leukemia/lymphoma (ATLL) cell lines, the mRNA and protein level of c-MYC is higher than normal due to the aberrations of FBXW7 expression, which is correlated with ATLL proliferation and poor prognosis of patients." (PMID 35515121, 2022).
B-cell lymphoma (4 papers, 2015 to 2025). "Strong similarities were evident between B-cell lymphomas from golden retrievers and cocker spaniels, with recurrent mutations in TRAF3-MAP3K14 (28% of all cases), FBXW7 (25%), and POT1 (17%)." (PMID 26377837, 2015). "The top most significantly mutated genes in B-cell lymphomas are POT1, FBXW7, and TRAF3." (PMID 26377837, 2015).
cardiac hypertrophy (4 papers, 2019 to 2025). "F-box and WD repeat domain-containing 7 (FBXW7) were proven to regulate cardiac hypertrophy through the EZH2–SIX1 axis." (PMID 38615011, 2024). "A previous study reported that FBXW7 negatively regulates physical cardiac hypertrophy by inhibiting prohypertrophic HIFIF-1α-Postn signaling pathways and eventually promoting inactivation of Akt." (PMID 31341888, 2019). "FBXW7 regulates EZH2-SIX1 signaling to accelerate pathological cardiac hypertrophy." (PMID 36660176, 2023). "Taken together, our study indicates that miR-195-5p promotes cardiac hypertrophy via targeting MFN2 and FBXW7 and may provide promising therapeutic strategies for interfering cardiac hypertrophy." (PMID 31341888, 2019).
diabetes (4 papers, 2021 to 2022). "FBXW7 gene expression is positively correlated with glycolipid metabolism and is associated with diabetes in animal models." (PMID 34372947, 2021). "Our findings illumined a novel mechanism of the circ_CLASP2/miR-140-5p/FBXW7 axis in diabetes-associated endothelial dysfunction." (PMID 33776760, 2021).
endometrioid adenocarcinoma (4 papers, 2017 to 2025). An adenocarcinoma characterized by the presence of malignant glandular epithelial cells resembling endometrial cells. "In the COSMIC database, the same FBXW7 mutation was found in cervical squamous cell carcinoma and endometrioid carcinoma, and the same MAP3K1 mutation was found in cutaneous squamous cell carcinoma." (PMID 32429412, 2020). "They observed that the inactivation of Fbxw7 and PTEN led to endometrioid intraepithelial neoplasia (EIN) and well-differentiated endometrioid adenocarcinomas." (PMID 40731786, 2025).
Ewing sarcoma (4 papers, 2022 to 2025). A small round cell tumor that lacks morphologic, immunohistochemical, and electron microscopic evidence of neuroectodermal differentiation. "In Ewing sarcoma, for instance, KDM5B attenuates FBXW7 transcription, leading to CCNE1 accumulation and enhanced proliferation." (PMID 40370434, 2025).
intestinal cancer (4 papers, 2018 to 2025).
lung squamous cell carcinoma (4 papers, 2018 to 2024). "Lung squamous cell carcinoma (cBioportal analysis, TCGA, Firehose Legacy) datasets show that mutations in FBXW7 significantly affect patient survival." (PMID 35346215, 2022). "In lung squamous cell carcinoma, mutations in the FBXW7 gene have been observed to affect survival in experimental animal models." (PMID 35346215, 2022). "Cancer Genome Atlas data suggests that deletion of FBXW7 occurs in 31% of lung adenocarcinomas (LADC) and 63% of lung squamous cell carcinomas (LSCC)." (PMID 35346215, 2022).
malignant glioma (4 papers, 2018 to 2024). A grade III or grade IV glioma arising from the central nervous system. "Additionally, the circRNA, circ-FBXW7, directly encodes the protein FBXW7-185aa and cooperates with the FBXW7 protein in linear transcripts to stabilize c-Myc and inhibit the occurrence and progression of malignant glioma." (PMID 33777729, 2021). "FBXW7-185aa, a protein encoded by Circ-FBXW7 with no clear subcellular localization identified to date, reduces the half-life of c-Myc by antagonizing USP28-induced stabilization of c-Myc, thereby impeding the development of malignant gliomas." (PMID 38622617, 2024).
metastatic melanoma (4 papers, 2015 to 2025). A melanoma that has spread from its primary site to another anatomic site. "FBXW7 expression was reduced in primary and metastatic melanoma compared with dysplastic and normal nevi and an increase in FBXW7 expression was significantly correlated with a better 5-year patient survival." (PMID 32850962, 2020).
pulmonary fibrosis (4 papers, 2021 to 2025). Chronic progressive interstitial lung disorder characterized by the replacement of the lung tissue by connective tissue, leading to progressive dyspnea, respiratory failure, or right heart failure. "Fbxw7 plays a key role as an inhibitor in the progression of pulmonary fibrosis (PF) in bleomycin-treated mice." (PMID 40901482, 2025). "In conclusion, our study revealed that Fbxw7 plays a crucial role in regulating pulmonary fibrosis progression." (PMID 35069531, 2021). "We found that decreased expression of E3 ubiquitin ligase Fbxw7 in peripheral blood mononuclear cells (PBMCs) was significantly related to the severity of pulmonary fibrosis in IPF patients." (PMID 35069531, 2021). "Our data showed that more monocytes are recruited into the lung tissues and BALF of Fbxw7-KO mice, these monocytes further differentiate into profibrogenic macrophages and then participate in the development of pulmonary fibrosis." (PMID 35069531, 2021). "We then used the bleomycin-induced mouse model of pulmonary fibrosis to observe the expression of Fbxw7 in lung tissues and peripheral blood monocytes." (PMID 35069531, 2021). "Myeloid-specific deletion of Fbxw7 exacerbates pulmonary fibrosis by inhibiting c-Jun degradation and upregulating TGF-β expression in macrophages." (PMID 35069531, 2021). "Fbxw7 is identified to be a crucial suppressing factor for pulmonary fibrosis development and progression in a mouse model induced by intratracheal bleomycin treatment." (PMID 35069531, 2021). "The Fbxw7 promoter can be regulated through epigenetic mechanism during lung fibrosis, including histone modifications." (PMID 35069531, 2021). "However, another recent study proposed that FBXW7 promotes senescence and pulmonary fibrosis, a typical age-related disease, by targeting the telomere protein TPP1 for degradation and accelerating the uncapping of telomere." (PMID 36104351, 2022). "Moreover, the expression of Fbxw7 in the macrophages in mice pulmonary fibrosis tissue was markedly decreased compared with those in healthy control subjects detected by immunofluorescence staining." (PMID 35069531, 2021). "Myeloid cell-specific Fbxw7 deletion increases pulmonary monocyte-macrophages accumulation in lung tissue, and eventually promotes bleomycin-induced collagen deposition and progressive pulmonary fibrosis." (PMID 35069531, 2021). "In this study, we demonstrated that the deletion of Fbxw7 in the myeloid lineages aggravates bleomycin-induced lung injury, collagen deposition, and monocyte recruitment, and eventually leads to the exacerbation of pulmonary fibrosis in mice." (PMID 35069531, 2021). "We speculate the function of Ezh2 in inducing the increase of H3K27me3 at Fbxw7 promotor and silencing of Fbxw7 gene might also be involved in regulating pulmonary fibrosis." (PMID 35069531, 2021). "Recent studies suggest that enhancer of zest homolog 2 (Ezh2) may increase H3K27me3 methylation at the Fbxw7 promoter, potentially repressing Fbxw7 expression, while IL-4 could reduce Fbxw7 activity to inhibit c-Jun degradation in fibrotic environments, thereby impacting pulmonary fibrosis." (PMID 40901482, 2025). "Collectively, these data further support that Fbxw7 deletion in myeloid cells can exacerbate bleomycin-induced production of TGF-β and promote the development of pulmonary fibrosis." (PMID 35069531, 2021). "In terms of the mechanism, the Fbxw7 deletion promoted the TGF-β expression in macrophages through reducing c-Jun ubiquitination, thereby aggravating the severity of pulmonary fibrosis." (PMID 35069531, 2021). "Taken together, Fbxw7 deletion leads to the upregulation of TGF-β expression and severity of pulmonary fibrosis through the regulation of c-Jun." (PMID 35069531, 2021).
pulmonary fibrosis (continued). "In addition, miR-2116-3p was shown to interact with and inhibit PIWIL1, and silencing of PIWIL1 was reported to upregulate FBXW7, which is a component of E3 ubiquitin-protein ligase complex and was observed to induce expression of fibrotic genes including fibronectin during pulmonary fibrosis." (PMID 34715879, 2021). "After 21 days of bleomycin-induced pulmonary fibrosis in mice, Fbxw7 knockout did not increase CD64+SiglecF+ AMs accumulation, but significantly increased CD11b+Ly6C+ monocytes recruitment in BALF." (PMID 35069531, 2021). "The absence of Fbxw7 leads to elevated TGF-β expression in macrophages by diminishing c-Jun ubiquitination, thus intensifying pulmonary fibrosis." (PMID 40901482, 2025).
rectal cancer (4 papers, 2019 to 2025). A primary or metastatic malignant neoplasm that affects the rectum. "BRAF, FBXW7, PTEN, and SMAD4 mutations were observed in 20.7% of patients with rectal carcinoma." (PMID 36142267, 2022).
scrapie (4 papers, 2015 to 2021). A fatal disease of the nervous system in sheep and goats, characterized by pruritus, debility, and locomotor incoordination. "Downregulation of these positive autophagy gene regulators (Becn1, Fbxw7, Gas5 and Atg5) has been described in the CNS of scrapie-infected mice (both wild-type or transgenic) and naturally scrapie infected sheep." (PMID 34283400, 2021). "On the contrary, the encoded protein of FBXW7 is upregulated at the early stage of infection in the scrapie murine brain cell line SMB-S15 and in brains of scrapie-agent 263K-infected hamsters, leading to degradation of mTORC1 and increase of autophagic flux." (PMID 32984276, 2020). "More recently, we found that FBXW7 (F-box and WD repeat domain containing 7) is responsible for the induction of mTOR degradation and for the ability of endogenous autophagy to counteract prion replication in the scrapie infected cell line SMB-S1516." (PMID 26423766, 2015).
T-cell leukemia (4 papers, 2018 to 2024). A malignant disease of the T-lymphocytes in the bone marrow, thymus, and/or blood. "Notable examples include NOTCH1, PHF6, and FBXW7, which are well-acknowledged for their role in T-cell leukemia, as well as BRAF, which was exclusively predicted in the hairy-cell group, in accordance with its recognized function as a marker for HCL." (PMID 38769532, 2024). "In the same context, recent evidence has revealed that mutation or lack of expression of FBXW7 contributes to BET inhibitors’ resistance, as in the case of T-cell leukemia cells by disruption of c-Myc degradation and its subsequent accumulation." (PMID 36934104, 2023).
acute myeloid leukemia (3 papers, 2021 to 2023). Acute myeloid leukemia (AML) is a group of neoplasms arising from precursor cells committed to the myeloid cell-line differentiation. "Besides its contribution to myeloid development, particularly to granulocyte and macrophage differentiation and to the pathogenesis of acute myeloid leukemia (AML), miR-223 is induced by active NOTCH1 and participates in T-ALL leukemogenesis by repressing the tumor suppressor FBXW7." (PMID 36674902, 2023).
breast tumor (3 papers, 2007 to 2015). "However, analysis of more than 151 primary breast tumor specimens showed that FBXW7/hCDC4 mutations are rare in this malignancy." (PMID 21122106, 2010). "In this study, we report for the first time promoter specific methylation of the FBXW7/hCDC4-β isoform in primary breast tumors." (PMID 21122106, 2010). "Two independent cohorts of primary breast tumors were analyzed and promoter hypermethylation was found to correlate with downregulation of FBXW7/hCDC4-β mRNA expression." (PMID 21122106, 2010). "Since we confirmed the synthetic lethal effect of FBXW7 knockdown with MYCER activation in MCF10A-MYCER cells, next we elected to examine the correlation between expression of FBXW7 and MYC in various breast tumor subtypes." (PMID 25669969, 2015). "After standard data quality gene filtering methods were employed, 19 out of 21 genes were present (FBXW7 and PIN1 gave very low signal intensities) in the clustering analysis and clearly exhibited significant variation in expression across the 194 breast tumors." (PMID 17224074, 2007).
cervical squamous cell carcinoma (3 papers, 2020 to 2025). A squamous cell carcinoma arising from the cervical epithelium. "In cervical squamous cell carcinomas, the commonly altered genes were PIK3CA (35.3%) and FBXW7 (17.6%), consistent with similar studies." (PMID 35267660, 2022).
colon adenoma (3 papers, 2013 to 2024). An adenoma that arises from the colon. "Among these mutated genes, mutations in APC, FBXW7, KIAA1409, COL4A6, FAM181A, TFR2 and NRXN3 were previously reported in colon adenomas or adenocarcinomas." (PMID 23301059, 2013).
colorectal adenocarcinoma (3 papers, 2013 to 2022). The most common type of colorectal carcinoma. "Moreover, ∼20% of patients with colorectal adenocarcinoma have somatic FBXW7 mutations, with altered FBXW7 expression contributing to tumor development and progression, while loss-of-function mutations are predicted to be deleterious." (PMID 35345853, 2022). "To confirm whether the widespread resistance to chemotherapy was also seen in human cancer cells, we generated FBXW7 knockout (FBXW7−/−) clones in the colorectal adenocarcinoma cell line DLD‐1." (PMID 35861150, 2022).
developmental delay (3 papers, 2024 to 2025). "FBXW7 mutations have been linked to impaired ubiquitination and a novel neurodevelopmental syndrome that exhibits developmental delay and intellectual disability." (PMID 41311387, 2025). "The FBXW7 is identified as the causative gene for developmental delay, hypotonia, and impaired language (OMIM #606278), characterized by global developmental delay, delayed speech, and distinctive facial features." (PMID 38884091, 2024).
gastric adenocarcinoma (3 papers, 2013 to 2017). "Quantitative reverse transcription PCR (qRT-PCR) assay was used to measure FBXW7 transcript levels in tumors paired with normal gastric tissue in 24 gastric adenocarcinoma patients." (PMID 28464881, 2017). "In conclusion, we have identified low FBXW7 expression as a potential powerful marker of poor prognosis in patients with gastric adenocarcinoma." (PMID 28464881, 2017). "All 546 gastric adenocarcinoma cases were then evaluated by tissue microarray and immunohistochemistry (IHC) for FBXW7 expression." (PMID 28464881, 2017). "Therefore, the aim of this study was to explore the relationship between FBXW7 expression and the clinicopathological characteristics as well as chemotherapeutic outcomes in gastric adenocarcinoma patients." (PMID 28464881, 2017). "Moreover, microRNA-25 has an antiapoptotic role in human gastric adenocarcinoma cells, possibly via inhibition of FBXW7, thus promoting the expression of oncogenes such as CCNE1 and MYC35." (PMID 28566720, 2017). "FBXW7 mRNA expression levels in gastric adenocarcinomas and paired noncancerous gastric tissue in 24 patients were examined by quantitative real time-PCR." (PMID 28464881, 2017).
Glucose intolerance (3 papers, 2019 to 2025). Glucose intolerance (GI) can be defined as dysglycemia that comprises both prediabetes and diabetes. "ENALA treatment for 24 h upregulated RNASEH2B, which is associated with headache and glucose intolerance, and downregulated FBXW7 (F-box and WD repeat domain containing 7), which is associated with constipation, through miRNA regulation." (PMID 40940770, 2025).
gynecologic cancers (3 papers, 2020 to 2023). "The FBXW7 gene is commonly mutated or deleted in numerous types of cancer, including gynecologic cancers (GCs)." (PMID 37408248, 2023).
Huntington disease (3 papers, 2009 to 2025). Huntington disease (HD) is a rare neurodegenerative disorder of the central nervous system characterized by unwanted choreatic movements, behavioral and psychiatric disturbances and dementia. "These include genes in the pathways for amyotrophic lateral sclerosis (NEF3, NEFL, NEFH), Huntington's disease (CALM3, CLTC, CLTB), neurodegenerative disorders (APLP1, NEFH, FBXW7), Parkinson's disease (GPR37) and prion disease (APLP1, NFE2L2)." (PMID 19948073, 2009).